FASN (fatty acid synthase)
Diseases named in the same sentence as FASN in open-access papers (continued):
Sharing a sentence is not in itself a finding about the gene and the disease.
Cerebral ischemia (1 paper, 2023). Restriction of arterial blood supply to the brain associated with insufficient oxygenation to support the metabolic requirements of the tissue. "Therefore, we hypothesized that GTA could promote lipogenesis in astrocytes and improve BBB repair after cerebral ischemia, and FASN mediated IL-33 upregulation might be involved." (PMID 37968698, 2023). "Data showed that after cerebral ischemia and GTA treatment, C75 didn’t affect the protein level of FASN, while FASN shRNA decreased the protein level of FASN in astrocytes in the peri-infarct area (P < 0.01)." (PMID 37968698, 2023).
cholestasis (1 paper, 2020). Impairment of the bile flow caused by obstruction within the liver, or outside the liver in the bile duct system. "Similarly, our cell culture models of cholestasis demonstrated increased activation of AMPK and CREB along with downregulation of FASN and PLIN2 in HepG2 cells, emphasizing the possible role of bile acid in lipid metabolism during cholestatic liver injury." (PMID 32612285, 2020).
chondrosarcoma (1 paper, 2021). A malignant cartilaginous matrix-producing mesenchymal neoplasm arising from the bone and soft tissue. "Interestingly, chondrosarcomas with high expression levels of two regulators of acylcarnitine metabolism, CPT1A and FASN, displayed worse patient outcome." (PMID 33762012, 2021).
chronic myeloid leukemia (1 paper, 2024). "We chose the chronic myeloid leukemia (CML)-derived, near-haploid cell line HAP1, in which CRISPR/Cas9-mediated knockdown of the FASN gene has been previously established as a suitable model system for defective de novo FA synthesis." (PMID 39349429, 2024).
cognitive decline (1 paper, 2025). "Given the increasing body of evidence linking HSV-1 to the onset of AD and the demonstrated neuroprotective effects of CMS121 — a fisetin-derived FASN inhibitor (FASNi) that reduces cognitive decline in mice — we aimed to evaluate its impact on HSV-1 replication." (PMID 40327680, 2025).
colon adenoma (1 paper, 2025). An adenoma that arises from the colon. "Strikingly, the in vivo inhibition of FASN in nATF6IEC mice results in the prevention of colon adenoma development." (PMID 40890536, 2025).
dermatitis (1 paper, 2018). An inflammatory process affecting the skin. "Increased immunohistochemical labeling of the lower epidermis for fatty acid synthase was reported in various forms of dermatitis." (PMID 29698466, 2018).
developmental epileptic encephalopathy (1 paper, 2022). "In addition, de novo mutations in FASN have been associated with developmental epileptic encephalopathy, further indicating relevance of FASN-dependent lipid metabolism for human brain development and disease." (PMID 34996870, 2022). "Moreover, several recently identified de novo mutations in human FASN have been associated with developmental epileptic encephalopathy, further indicating relevance of FASN for human brain development and disease." (PMID 34996870, 2022).
diabetic nephropathy (1 paper, 2022). "Bailing Capsule activated the expression of PPARα, ACOX1 (acyl-CoA oxidase 1), and SCD (stearoyl-CoA desaturase) in diabetic nephropathy while suppressing the expression of FASN (fatty acid synthase)." (PMID 36091833, 2022).
diffuse gastric adenocarcinoma (1 paper, 2026). An adenocarcinoma arising from the stomach. "Background/Objectives: To evaluate the immunohistochemical expression of hexokinase-2 (HK2), glutaminase-1 (GLS1), and fatty acid synthase (FASN) and its prognostic significance in diffuse gastric adenocarcinoma." (PMID 41892863, 2026).
E. coli infection (1 paper, 2018). "Importantly, based on our results, E. coli infection causes down-regulation of genes encoding lipid biosynthesis enzymes including ALOX15, FASN, GPAM, TM7SF2 that are involved in milk production." (PMID 29470489, 2018).
enterocolitis (1 paper, 2024). An inflammatory process affecting the small intestine and colon. "Deficiency of fatty acid synthase (FASN) in the colonic epithelium blocks mucin 2 (MUC2) production, disrupts the intestinal barrier, and induces enterocolitis." (PMID 39465140, 2024).
epilepsy (1 paper, 2021). A brain disorder characterized by episodes of abnormally increased neuronal discharge resulting in transient episodes of sensory or motor neurological dysfunction, or psychic dysfunction. "Carbamazepine increased the expression levels of FASN, suppressed Wnt/β-catenin expression, and was widely used in the treatment of epilepsy." (PMID 34664012, 2021).
epileptic encephalopathies (1 paper, 2021). "De novo mutation of FASN in synaptic transmission genes was detected in epileptic encephalopathies via synaptic dysregulation." (PMID 34664012, 2021).
Ewing sarcoma (1 paper, 2020). A small round cell tumor that lacks morphologic, immunohistochemical, and electron microscopic evidence of neuroectodermal differentiation. "These lipid metabolism processes are required for cell survival of Ewing sarcoma, as evidenced by the cytotoxicity of their inhibitors (Orlistat against FASN and Myriocin against SPTLC1)." (PMID 33080033, 2020). "Moreover, Orlistat, a specific FASN inhibitor, potently inhibited cell proliferation both in vitro and in vivo where each mouse carried two explants formed by A673 cells, suggesting the biological importance of fatty-acid synthesis pathway in Ewing sarcoma cells." (PMID 33080033, 2020). "In addition, silencing of either FASN, SCD or SPTLC1 markedly reduced cell proliferation of Ewing sarcoma, further corroborating this conclusion." (PMID 33080033, 2020).
fibrosarcoma (1 paper, 2018). A malignant mesenchymal fibroblastic neoplasm affecting the soft tissue and bone. "In human UPS and fibrosarcoma CPT1A is modestly elevated or unchanged relative to normal tissues, whereas muscle-specific CPT1B is lost and FASN is increased." (PMID 30382078, 2018).
Flavivirus Infections (1 paper, 2017). Infections with viruses of the genus FLAVIVIRUS, family FLAVIVIRIDAE. "Small molecules that target enzymes associated with fatty acid and lipid metabolism, such as fatty-acid synthase, have been associated with a reduction in mosquito-borne flavivirus infection." (PMID 28086865, 2017).
HCMV infection (1 paper, 2025). "HCMV infection upregulates FASN transcription, and C75 treatment of HCMV-infected fibroblast cells reduced infectious HCMV virion production, without inducing cell toxicity or apoptosis." (PMID 40558086, 2025). "HCMV infection also increased both the number of lipid droplets and the production of very long-chain fatty acids; however, it is unclear if these changes are FASN-dependent." (PMID 40558086, 2025).
Headache (1 paper, 2025). Cephalgia, or pain sensed in various parts of the head, not confined to the area of distribution of any nerve. "Similarly, genes identified for headache (e.g., ETFA, GRHPR, MMAB) and facial pain (e.g., FASN, SPHK2) also consistently showed protective trends at both the expression and protein levels." (PMID 40943610, 2025).
hepatoblastoma (1 paper, 2024). Hepatoblastoma (HB) is a malignant hepatic tumor and is the most common pediatric liver cancer. "Inhibitors of glycolysis (e.g., 2-deoxyglucose) or fatty acid synthesis (e.g., FASN inhibitors) are being explored as potential therapies for hepatoblastoma." (PMID 39596558, 2024). "FASN inhibitors and other metabolic agents, although still in the early phases of clinical evaluation, show promise in preclinical models of hepatoblastoma." (PMID 39596558, 2024).
hypercoagulability (1 paper, 2022). "Due to their recent discovery and development, lipase and fatty acid synthase inhibitors must be further evaluated to ascertain their effectiveness at reducing thrombotic risk in patients with hypercoagulability." (PMID 36142215, 2022).
hypercortisolism (1 paper, 2020). "In a previous study, patients with CS had increased fatty acid synthase expression than controls owing to the suppression of AMP-activated protein kinase (AMPK) activity in visceral adipose tissue, which of interest was correlated with the severity of hypercortisolism." (PMID 33633684, 2020).
inflammatory bowel disease (1 paper, 2022). A spectrum of small and large bowel inflammatory diseases of unknown etiology. "In conclusion, Hakai regulates FASN ubiquitination and degradation, resulting in the regulation of FASN-mediated lipid accumulation, which is associated to the development of inflammatory bowel disease." (PMID 36266428, 2022).
insulin-resistant diabetic (1 paper, 2019). "In insulin-resistant diabetic mice, overexpression of STAT3 not only increases plasma triglyceride and total cholesterol levels but also promotes transcription of lipid synthesis-related enzymes such as fatty acid synthase and acetyl-CoA carboxylase." (PMID 31223625, 2019).
intestinal polyp (1 paper, 2022). Discrete abnormal tissue masses that protrude into the lumen of the intestine. "Even in ApcMin/+ mice (that spontaneously develop intestinal polyps), the OO-enriched diet reduced polyp number and volume through a reduction of proliferation as well as proapoptotic effect by inhibiting fatty acid synthase and HMGCoA reductase gene expression." (PMID 35215560, 2022).
intestinal tumors (1 paper, 2020). "In agreement with in vitro data, the analysis of intestinal tumors from mice with hetero- and homozygous deletions of FASN on C57BL/6-Apc/Cre background showed that deletion of FASN significantly upregulates CD36 expression." (PMID 32850342, 2020).
invasive ductal carcinoma (1 paper, 2024). "FASN-mediated changes of specific fatty acids has been linked to promote cancer migration in both cell lines, and patients with invasive ductal carcinoma." (PMID 39232464, 2024).
iron overload (1 paper, 2024). "In conclusion, FA can protect the liver from lipid and bile acid metabolism disorders caused by iron overload by targeting FASN and CYP7A1." (PMID 39594419, 2024).
laryngeal carcinoma (1 paper, 2022). Carcinoma that arises from the laryngeal epithelium. "The level of phosphatase and tensin homolog deleted on chromosome ten (PTEN) is down-regulated in laryngeal cancer, a gene involved in regulating lipid metabolism by affecting Akt/mTOR signaling, FASN and ACC expression, and lipogenesis." (PMID 36355170, 2022).
latent infection (1 paper, 2025). "Further research is required to better understand the FASN dependency in EBV B-cell latent infection." (PMID 40558086, 2025). "Separate studies reported that LMP1, the major transforming oncoprotein in vitro during EBV latent infection, upregulated FASN levels in both nasopharyngeal carcinoma and B-cells, through different mechanisms." (PMID 40558086, 2025).
microcephaly (1 paper, 2022). A congenital or acquired developmental disorder in which the circumference of the head is smaller than normal for the person's age and sex. "Here, we identify a pivotal role of fatty acid synthase (FASN)-dependent de novo lipogenesis for mouse and human brain development, as genetic deletion of FASN leads to microcephaly in the developing mouse cortex and cortical malformations in human embryonic stem cell–derived forebrain organoids." (PMID 34996870, 2022).
nutritional deficiency (1 paper, 2021). "Furthermore, results of the recent studies suggest that the genes involved in hepatic lipid synthesis (ACACA, FASN, LPL, SCD1, FADS1, and FADS2) were down-regulated over nutritional deficiency." (PMID 35111749, 2021).
osteoarthritis (1 paper, 2023). A noninflammatory degenerative joint disease occurring chiefly in older persons, characterized by degeneration of the articular cartilage, hypertrophy of bone at the margins and changes in the synovial membrane. "Herein, we clarify that CircRREB1 is highly expressed in secondary generation chondrocytes and its deficiency can alleviate FASN related senescent phenotypes and osteoarthritis progression." (PMID 37640697, 2023). "Here, the authors show that that CircRREB1 is highly expressed in second generation chondrocytes and its deficiency can alleviate FASN related senescent phenotypes and osteoarthritis progression." (PMID 37640697, 2023).
ovarian clear cell cancer (1 paper, 2025). An invasive malignant neoplasm that arises from the ovary and is characterized by a predominance of clear and hobnail malignant epithelial cells. "In our previous work, we demonstrated that NAC1/FASN overexpression is critical for the growth and survival of a subset of ovarian clear cell carcinomas (OCCC)." (PMID 40430078, 2025).
ovarian serous carcinoma (1 paper, 2010). "In conclusion, we show that NAC1 is essential for FASN expression in ovarian serous carcinomas and the expression of FASN significantly correlates with tumor recurrence and disease aggressiveness." (PMID 20508725, 2010). "This NAC1-dependent FASN expression in protein level is further supported by its mRNA level and the positive correlation between NAC1 and FASN immunointensities in ovarian serous carcinoma samples." (PMID 20508725, 2010). "New generation FASN inhibitors, like C93, deserve consideration in future clinical trials involving advanced ovarian serous carcinomas, particularly those that are refractory to paclitaxel and platinum drugs." (PMID 20508725, 2010). "We also demonstrate that FASN expression is highly correlated with the status of recurrent chemoresistant ovarian serous carcinomas and is independently correlated with poor overall survival." (PMID 20508725, 2010). "The second finding in the current study involves the positive correlation between FASN expression and recurrence status in ovarian serous carcinoma tissue." (PMID 20508725, 2010). "Our findings also indicate that FASN is a novel biomarker for recurrent ovarian serous carcinoma and its enzyme activity is essential for the survival of chemoresistant tumor cells." (PMID 20508725, 2010). "Immunohistochemistry showed that NAC1 and FASN immunointensities in ovarian serous carcinoma tissues had a highly significant correlation (P < .0001)." (PMID 20508725, 2010). "Since NAC1 has been shown to be highly expressed in recurrent rather than primary high-grade ovarian serous carcinomas, we expect that FASN expression levels will follow the same pattern." (PMID 20508725, 2010). "Therefore, FASN inhibitors may contribute to antioncogenesis by suppressing tumor-promoting signaling pathways such as AKT, a pathway that is frequently activated in ovarian serous carcinoma." (PMID 20508725, 2010).
parasite infection (1 paper, 2025). "FASN expression showed positive correlations with chemokine signaling, cytokine-cytokine receptor interaction, and hematopoietic cell lineage pathways, but negative correlations with parasite infection-related pathways and natural killer (NK) cell-mediated cytotoxicity." (PMID 40703521, 2025).
pemphigus (1 paper, 2025). Pemphigus is a group of rare autoimmune diseases that cause blistering of the skin and mucous membranes (mouth, nose, throat, eyes, and genitals).This conditioncan occur at any age, but often strikes people in middle or older age. "Differential expression analysis was conducted to investigate the expression patterns of the five genes (XBP1, FBXO45, SAT2, AIFM1, and ACSL4) and eight other DEGs associated with ferroptosis (G3BP1, WBP11, TET2, IRF8, FASN, GDPD5, H1-4, and HUWE1) in both the pemphigus and control groups." (PMID 40612574, 2025).
periodontitis (1 paper, 2025). An acute or chronic inflammatory process that affects the tissues that surround and support the teeth. "This study demonstrated that increased NAMPT in periodontitis promotes endothelial permeability by modulating FASN-mediated lipogenesis, thereby contributing to bone loss in periodontitis." (PMID 40303304, 2025). "Using FASN inhibitor orlistat, we further demonstrate its effect on suppression of vascular leakage and bone resorption of periodontitis in vivo." (PMID 40303304, 2025).
phospholipidosis (1 paper, 2023). "In particular, the upregulation of the genes MSMO1, IDI1, LSS, and HMGCR suggested enhanced synthesis of cholesterol, and the upregulation of FASN suggested an increased synthesis of fatty acids that may in turn induce phospholipidosis." (PMID 37745076, 2023).
preeclampsia (1 paper, 2016). Preeclampsia is a hypertensive disorder of pregnancy that is characterized by new-onset hypertension with proteinuria presenting after 20 weeks of gestation, and depending on mild or severe forms may initially present with severe headache, visual disturbances, and hyperreflexia. "The exact link between circulating FASN and blood pressure in women with pathological conditions, such as preeclampsia or metabolic disorders cannot be discerned in our healthy study population." (PMID 27090298, 2016).
pregnancy toxemia (1 paper, 2025). "PCR-DNA sequence analysis revealed that the amplified fragments of IL-6 (627 bp), IL-8 (264 bp), FASN (381 bp), SOD3 (393 bp), HMOX1 (460 bp), and ACACA (477 bp) differed between healthy goats and those affected by pregnancy toxemia (PT)." (PMID 41012815, 2025).
prostate (1 paper, 2025). "Similarly, FASN was reported to exhibit nuclear localization in prostate cancer cells." (PMID 39971971, 2025).
pyometra (1 paper, 2025). "This study demonstrates that dysregulated lipid metabolism is a critical driver of canine pyometra progression, characterized by coordinated upregulation of ACC1, FASN, SREBP-1c, PLIN2 and suppression of PPARα and PGC1α." (PMID 40082867, 2025). "The expression of related lipid synthesis proteins such as ACC1, FASN, SREBP-1c, and PLIN2 was upregulated, while PPARα and PGC1α were downregulated in bitches with pyometra." (PMID 40082867, 2025).
retinal degeneration (1 paper, 2018). Degeneration of the retina. "Mutations in FASN have not been described that cause human retinal degeneration, perhaps because most of these mutations would be predicted to be lethal." (PMID 29321376, 2018).
retinitis pigmentosa (1 paper, 2018). Retinitis pigmentosa (RP) is an inherited retinal dystrophy leading to progressive loss of the photoreceptors and retinal pigment epithelium and resulting in blindness usually after several decades. "Retinas lacking fatty acid synthase develop normally but — independent of light exposure, high-fat feeding, or fenofibrate treatment — subsequently undergo rapidly progressive neurodegeneration characterized by global loss of retinal neurons and resembling retinitis pigmentosa." (PMID 29321376, 2018).
Right ventricular hypertrophy (1 paper, 2026). In this case the right ventricle is more muscular than normal, causing a characteristic boot-shaped (coeur-en-sabot) appearance as seen on anterior- posterior chest x-rays. "Inhibition of fatty acid synthase can reduce pulmonary vascular remodeling, right ventricular pressure, and right ventricular hypertrophy and improve endothelial function, thereby reducing PH, indicating that fatty acid metabolism is also involved in the process of PH." (PMID 41492472, 2026).
Stroke (1 paper, 2023). Sudden impairment of blood flow to a part of the brain due to occlusion or rupture of an artery to the brain. "We previously found that FASN, the driving enzyme of lipogenesis, was highly expressed in reactive astrocytes after stroke." (PMID 37968698, 2023).
systemic candidiasis (1 paper, 2025). "The avirulence of the encoded gene (FAS2) -deleted mutant in a mouse model of systemic candidiasis is not due to its fitness defects, because sufficient exogenous fatty acids in serum can overcome FASN inhibition." (PMID 40138332, 2025).